UBQLN3 (ubiquilin 3)
Synonyms: TUP-1
Tractability: PROTAC: ubiquitination databases record sites on it.
Gene: Protein-coding gene on chromosome 11 (5,507,300 to 5,509,958, reverse strand). Ensembl gene ENSG00000175520.
Gene Ontology:
Molecular function: protein binding
Biological process: ubiquitin-dependent protein catabolic process; regulation of proteasomal protein catabolic process
Genetic constraint (gnomAD): Loss-of-function variants: 1 observed, 2.8 expected, observed/expected ratio (o/e) 0.36, 90% interval 0.12 to 1.53. That is too few expected variants to judge how well the gene tolerates losing a copy. Missense variants: 876 observed, 817.48 expected, observed/expected ratio (o/e) 1.07, 90% interval 1.01 to 1.13. Synonymous variants: 333 observed, 317.51 expected, observed/expected ratio (o/e) 1.05, 90% interval 0.96 to 1.15.
Homologues: Orthologues: chimpanzee UBQLN3 (98% identical), macaque UBQLN3 (95% identical), rabbit UBQLN3 (80% identical), dog UBQLN3 (79% identical), rat Ubqln3 (75% identical), mouse Ubqln3 (74% identical), guinea pig UBQLN3 (71% identical), pig UBQLN3 (67% identical), Drosophila melanogaster CG31528 (14% identical). Paralogues in human: UBQLN1 (43% identical), UBQLN2 (41% identical), UBQLN4 (37% identical), UBQLNL (18% identical), UBL7 (13% identical).
Diseases named in the same sentence as UBQLN3 in open-access papers:
UBQLN3 is named in the same sentence as 3 diseases in open-access papers, as found by Europe PMC text mining. Sharing a sentence is not in itself a finding about the gene and the disease. The quoted sentences say what the papers report.
lung adenocarcinoma (1 paper, 2023). A carcinoma that arises from the lung and is characterized by the presence of malignant glandular epithelial cells. "Interestingly, we observed an increase in the expression of oncogene MYC following the loss of UBQLN1 or UBQLN2, but not with UBQLN3 or UBQLN4 in lung adenocarcinoma cells." (PMID 37444499, 2023).
pancreatic cancer (1 paper, 2023). "UBQLN3 missense mutations have been reported in lung, breast, central nervous system, and pancreatic cancer, although their functional role in cancer remains unexplored." (PMID 37867524, 2023).
cancer (3 papers, 2020 to 2023). A tumor composed of atypical neoplastic, often pleomorphic cells that invade other tissues. "UBQLN3 belongs to the ubiquilins protein family, essential factors for the maintenance of cell proteostasis and found involved in cancer progression." (PMID 37867524, 2023). "The heatmap indicated that UBQLN4 was positively related to UBQLN1 and UBQLN2 in most cancers with statistical significance, while few correlations were found between UBQLN4 and the remaining two members (UBQLN3 and UBQLNL)." (PMID 34539785, 2021).